NF2 (NF2, moesin-ezrin-radixin like (MERLIN) tumor suppressor)
Diseases named in the same sentence as NF2 in open-access papers (continued):
Sharing a sentence is not in itself a finding about the gene and the disease.
tumor (continued). "Although NF2 loss is known to contribute to tumor metastasis, no direct strategy has been developed to overcome NF2 deficiency during cancer progression." (PMID 37730636, 2023). "Moreover, recent pancancer studies by The Cancer Genome Atlas Research in 9125 tumor samples have revealed that Hippo pathway components are widely altered in human cancers, such as downregulation of NF2, FAT1, TAOK1-3, WW45, and LATS1/2." (PMID 37211598, 2023). "The relationship between the specific mutation of the NF2 gene and the effect of the inactivation of both NF2 alleles on tumor growth has not yet been described in VSs." (PMID 36672540, 2022). "However, erlotinib was ineffective in NF2-related VSs for tumor shrinkage and improving hearing outcome." (PMID 35628268, 2022). "In this study, we first detected the occurrence of NF2 inactivation in the tumor samples." (PMID 36267986, 2022). "Comparing somatic mutation rates in SMGs between clusters using binomial regression identified PIK3CA (FDR = 0.001) and EP300 (FDR = 0.046) mutations as disproportionally more common in C1 tumours and STK11 (FDR = 0.005) and NF2 (FDR = 0.045) as enriched in C2 tumours." (PMID 36207323, 2022). "This is because NF2 knockout facilitates tumor cell metastasis, which GPX4 knockout inhibits." (PMID 35911967, 2022). "Frequent inactivation of the tumour suppressors BAP1, NF2 and P16 may differentially sensitise tumours to treatments." (PMID 36497318, 2022). "Accessed September 02, 2021) and it is possible that this variant was acquired somatically in the tumor and is not related to NF2 disease." (PMID 35332608, 2022). "Therefore, NF2 is a “tumor suppressor” gene and, as such, the related syndrome is caused by loss-of-function mutations of this gene." (PMID 36077416, 2022). "They revealed “two-hit” alterations in the NF2 gene in every tumor." (PMID 35626200, 2022). "Our bioinformatic analysis showed that tumor angiogenesis-related proteins, including EGFR, FGF1, FGF2, VEGRR2, and PDGFRA, were in the top 15 key targets in the PPI network of QDSJ decoction treating NF2-associated VS." (PMID 36059985, 2022). "The abnormal expression of TEAD could modulate several cancer-associated genes, including MYC, KRAS, NF2, BRAF and LKB1, which had crucial roles in the regulation of tumor immunity." (PMID 35077390, 2022). "Nevertheless, in the NF2 population where VS tumors grow more rapidly than in sporadic cases, even an arrest of tumor growth could be advantageous." (PMID 36185258, 2022). "Atypical NF2 mutants demonstrate chromosomal instability, which might be related to tumor invasiveness." (PMID 35712491, 2022). "It is not known if MMe tumor cells from Cdkn2a+/−;Nf2+/− mice have any replication repair deficiency." (PMID 35804881, 2022). "Sometimes, diagnosis of NF2 is initially missed due to delayed contralateral tumor growth." (PMID 35455534, 2022). "This study effectively determined that BAP1, CDKN2A and NF2 alterations occur in pleural effusion-derived tumour cells at a higher frequency than what is typically seen in MM tumour samples, as well as identifying high frequency alterations for the TRAF7 and LATS2 genes." (PMID 34900693, 2021). "Other notable findings in this tumour included missense variants in NFKB2, NF2 and USP6." (PMID 37435187, 2021). "Nf2 is well‐known as a suppressor of cell proliferation and tumour." (PMID 34697858, 2021). "However, some studies have shown that larger VS tumors and those from NF2 patients have an overall lower rate of tumor control than those published for sporadic tumors that are small and medium sized." (PMID 34572805, 2021).
tumor (continued). "The NF2/Merlin tumour suppressor functions both at the cell cortex and nucleus and is a key mediator of contact inhibition but the molecular mechanisms remain unclear." (PMID 34424918, 2021). "For P10, these were a missense mutation, c.4207A > C, in KDM5C in the evDNA, and a frameshift mutation in NF2, c.814_817delACTA in the cfDNA that were not captured in tumor sequencing data." (PMID 34830979, 2021). "Finally, they concluded that main purpose should be the preservation of cranial nerve function as long as possible in combination with tumor control in case of NF2." (PMID 33804067, 2021). "Nevertheless, a number of key tumour suppressor genes are frequently affected, including those encoding cyclin-dependent kinase inhibitor 2A (CDKN2A), BRCA1-associated protein 1 (BAP1) and neurofibromin 2 (NF2)." (PMID 34226685, 2021). "NF2 is a well‐established tumor suppressor and an essential upstream regulator of Hippo signaling." (PMID 33818013, 2021). "This panel of cell lines was used to assess selectivity of pharmacological responses based on NF2 status and to distinguish the differences in compound responses between human and mouse NF2-related tumor cells to better predict the drug activity in animal models." (PMID 34264955, 2021). "In addition, the level of Merlin in Nf2−/− MMTV Neu+‐derived tumor tissue was significantly lower than in the tumors derived from Nf2fl/fl MMTV Neu + mice, suggesting that faster tumor onset was attributable to Nf2 deletion." (PMID 33410252, 2021). "We believe that more definitive criteria for this pattern should be established to diagnose this tumor in the absence of NF2 mutation analysis." (PMID 34680535, 2021). "Bevacizumab (Avastin®), a monoclonal antibody that neutralizes vascular endothelial growth factor (VEGF), is administered off-label to patients with NF2 and progressive VS, with ~36-41% of the patients experiencing durable hearing improvement and reduced tumor volume." (PMID 34604034, 2021). "These cells infiltrated also into NF2 tumors and decreased after tumor resection." (PMID 33604573, 2021). "Increased loss of chromosome 22q that encodes NF2, CHEK2, and SMARCB121 were observed in type 2 PRCC, which may implicate in carcinogenesis and tumor progression." (PMID 34489456, 2021). "NF2 is a known tumor-suppressing gene that acts as a guardian in the Hippo signaling pathway." (PMID 33173047, 2020). "Consecutively, diagnosis for NF2 may be largely delayed with the consequence of wasting the valuable time-window for monitoring VS tumor growth and hearing in the early stage." (PMID 32537663, 2020). "NF2 can also regulate formation of neovascularization in tumor via semaphorin 3F." (PMID 32422606, 2020). "The non-sRCCs were predominantly higher risk tumours; only 14 of the 268 (5%) had Hippo pathway alterations, involving NF2 (6/268), FAT1 (3/268), LATS1 (2/268), LATS2 (3/268) and YAP1 (1/268)." (PMID 31959902, 2020). "A LATS2 in-frame deletion insertion missense variant, SL425PP, was detected in the SB tumor from F8 that did not harbor NF2 or chromosome 22 alterations, raising the possibility of independent mutations in the NF2-Hippo pathway in this ED group." (PMID 31963394, 2020). "We found that the low expression of NF2 was related with the tumor stage." (PMID 32337368, 2020). "Therefore, parents can be counseled or send to genetic counseling in case of tumor manifestations typical for NF2 or the indetification of a typical skin schwannoma." (PMID 32537663, 2020). "Besides, YAP nuclear translocation is inhibited through NF2 to aggravate tumor invasiveness related to miR-296-3p and CTGF/CYR61." (PMID 32676008, 2020).
tumor (continued). "For example, YAP/TAZ inactivation may cause compensatory lysosome-mediated activation of MAPK signaling in NF2 tumor growth." (PMID 32960816, 2020). "Interestingly, the top enriched target was Nf2/Merlin, which is a known tumor suppressor gene and a regulator of Hippo signaling necessary for cell density control (Petrilli and Fernández-Valle, 2016)." (PMID 33185187, 2020). "The actual effect of NF2 loss on cell populations within a tumour is not known, although the literature does indicate a more immunosuppressive environment in higher grades." (PMID 32070062, 2020). "Finally, mechanistic studies in vitro and in vivo demonstrated that YAP1 inhibition or NF2 reconstitution impaired tumour growth and proliferation." (PMID 31959902, 2020). "PAK1-specific inhibitors CEP-1347 and WR-PAK18 selectively inhibited NF2-deficient tumor cells and did not contribute to NF2-positive tumor cells." (PMID 32337368, 2020). "The NF2 gene is involved in a variety of human tumors and may be a tumor suppressor gene, but its function and mechanism of action are not well understood." (PMID 32337368, 2020). "The drugs that inhibit the PI3K-Akt signaling pathway may be a potential therapeutic strategy for NF2 by antitumor activity against NF2-related tumor cells." (PMID 32733557, 2020). "Although pevonedistat has been tested in MPM in the context of NF2 loss and now is being tested in clinical trials for MPM, there has not been a mechanistic detail explaining the treatment efficacy in vivo and possible effects on the tumor microenvironment." (PMID 33233664, 2020). "Promoter methylation of NF2 is a key mechanism in Merlin expression and tumor development." (PMID 32244314, 2020). "Proteins oxidized by peroxynitrite could be exceptional targets for the development of tumor-directed therapies for the treatment of NF2 and possibly for treatment of other solid tumors." (PMID 31171721, 2019). "Jean hypothesized that NF2 regulates cell growth function, and its inactivation could be related to tumour progression and patient survival." (PMID 31470859, 2019). "However, the nonsteroidal sulfamate derivatives of 2ME2 effectively promoted nuclear fragmentation in both NF1 and NF2 null tumour cell lines." (PMID 31730023, 2019). "We therefore examined whether this effect was also observed in our studies of NF2-null tumour cells." (PMID 31730023, 2019). "NF2 was the most frequently affected gene in 44% of the tumor samples (n = 8/18)." (PMID 31470906, 2019). "Low PD-L1 expression was observed on tumor cells or endothelial cells in NF2 patients." (PMID 31848332, 2019). "Tumor extension, NF2 and MIB > 1.03% remained independent significant factors (data not shown)." (PMID 31291992, 2019). "Among NF2-associated VSs, no tumor showed progression over the observation period after SRS, yielding 100% PFR at 10–20 years; whereas among sporadic VSs, 2 (4.5%) tumors showed progression, yielding PFR of 93% at 10–20 years." (PMID 31591325, 2019). "Patients with an NF2 mutant tumor were on average older than those without the mutation (66.5 vs. 56.8 years, p = 0.010)." (PMID 31191822, 2019). "Alternate treatment options for NF2 tumours include inhibitors of the epidermal growth factor receptor (EGFR), inhibitors of the vascular endothelial growth factor (VEG-F), inhibitors of mTORC1, an inhibitor of platelet-derived growth factor (PDGF), and an inhibitor of histone deacetylase (HDAC)." (PMID 31730023, 2019). "We, therefore, explored the possibility that STX3451 and/or STX2895 could also block cell migration in NF2-null tumour cells using “wound-healing” assays as we had previously done for NF1 cells." (PMID 31730023, 2019). "Our data predicts that in the presence of active MYC, loss of either NF2 or YAP activity may reduce the growth potential of the transformed structures and, speculatively, result in desired therapeutic effects on tumour cells with high MYC activity." (PMID 29507319, 2018).
tumor (continued). "Findings in mouse models support the biological function of NF2 as a tumor suppressor gene." (PMID 29587439, 2018). "This suggests that inhibition of the Hippo pathway in NF2-deficient PRCC may have a therapeutic value and may selectively target the tumor cells." (PMID 29535838, 2018). "In addition to NF2 mutations, genetic LATS2 inactivation is observed in MM cases, such that LATS2 inactivation, and its effects tumor suppression, were initially identified in seven of 20 MM cell lines analyzed in vitro." (PMID 29565815, 2018). "Thus, mouse survival after asbestos exposure was tested in a well-studied MM mouse model, i.e. in mice heterozygous for the tumor suppressor NF2 either wild-type (C57-NF2+/−) or null-mutant (C57-NF2+/-CR−/−) for the Calb2 gene." (PMID 29928505, 2018). "Contact inhibition, a regulatory mechanism providing cell growth arrest at confluence in tissue culture, is frequently disrupted in cancer cells, and NF2-null cells grow to a significantly higher density compared to wild-type cells, suggesting that NF2 controls tumor progression." (PMID 29587439, 2018). "Dosage sensitivity of tumor growth to the Drosophila homolog of Yap, Yki, has been reported previously, and Yap heterozygosity can suppress liver overgrowth in mice mutant for the upstream Hippo pathway component NF2." (PMID 29340023, 2017). "Analysis of liver-specific Nf2 knockout mice and Nf2:Amot double knockout (DKO) mice showed Amot is required for hepatic ductal cell proliferation and tumor formation in the context of either Nf2 loss or DDC (3,5-diethoxycarbonyl-1,4-dihydrocollidine)-induced injury." (PMID 28464980, 2017). "In patients with mosaic NF2, the ‘first-hit’ NF2 gene mutation is often present at a low level in blood cells and is sometimes only detectable in tumour tissue but not in blood cells." (PMID 27921248, 2017). "In the mouse-liver, homozygous deletion of Nf2 results in tumor formation." (PMID 28464980, 2017). "To characterize super-enhancers associated with atypical tumours independent of the mutational background, we next compared atypical NF2 mutant samples to benign NF2 mutants and identified five super-enhancers with concordant changes in gene expression." (PMID 28195122, 2017). "The comparison between the genetic profiles of the two age groups with different clinical characteristics may establish a relationship between the detected NF2 gene status and tumour behaviours." (PMID 28710469, 2017). "As an important tumour suppressor, NF2 plays a major role in inhibiting the proliferation of cells." (PMID 28764788, 2017). "Further analysis would be necessary to establish whether alternative mechanisms, such as epigenetic silencing of NF2 gene expression, could be involved in the biallelic NF2 inactivation in these tumours." (PMID 27921248, 2017). "Nevertheless, as small number of RCC with NF2 mutations have been recently reported in pRCC15, 16 and collecting duct RCC34, it remains to be determined whether these tumours were distinct from or overlapped with our NF2 loss uRCC." (PMID 27713405, 2016). "Although NF2 basolateral plasma membrane staining was preserved in normal CP and CP tumors, a decreased expression and a more focal distribution was observed with increasing tumor grade." (PMID 27229317, 2016). "And VP was effective in delaying tumor progression in a NF2-depleted mouse liver model." (PMID 27738325, 2016). "This tendency is most likely due to the known tumor suppressor function of NF2." (PMID 27229317, 2016). "NF2 showed focal areas of basolateral plasma membrane staining in CP carcinoma that is important in demonstrating the CP origin of the tumor." (PMID 27229317, 2016).
tumor (continued). "For patients with sporadic VS who do not have NF2, RT is associated with long-term tumor control rates exceeding 95%." (PMID 28191549, 2016). "Nf2 heterozygous or homozygous mice have multiple malignant tumours." (PMID 26443326, 2015). "More than 25% of sporadic cases of NF2 are mosaic, with the mutation often detected only in tumor material and not in lymphocyte DNA." (PMID 26540169, 2015). "We previously identified the Mediator subunit, MED28, as a cytosolic binding partner of merlin, the Neurofibromatosis 2 (NF2) tumor suppressor, and thus MED28 is distinct in having a cytosolic role as an NF2 interacting protein as well as a nuclear role as a Mediator complex subunit." (PMID 26445504, 2015). "Then, we exploited the estimated VAF to select candidate alterations in NF2 gene in 34 samples with unknown genotype (30 blood and 4 tumor DNAs), demonstrating the suitability of our method." (PMID 26066488, 2015). "NF2, known as a tumor suppressor, is inactivated via phosphorylation." (PMID 25605020, 2015). "However, deletion of Nf2 in the liver reproducibly leads to a massive increase in liver mass and eventual tumours within one year." (PMID 26258444, 2015). "Taken together, due to a variety of organ systems being affected by NF2 disease, affected individuals may suffer from severe morbidity in addition to their tumor burden." (PMID 25012216, 2014). "The binding of EBP50 to the epidermal growth factor receptor (EGFR) and neurofibromin 2 (NF2) may also result in tumor suppression." (PMID 25120624, 2014). "Thus, this study highlights a new therapeutic implication on drug treatment for NF2 as well as other tumours/cancer." (PMID 25321473, 2014). "The Glu17Lys mutation of the AKT1 (chromosome 14q32.32) gene was one of the mutations found in tumor cell lines that had no genetic alterations in the NF2 gene." (PMID 25485306, 2014). "As proof that the retained genes include genuine drivers, we note that the list of genes recurrently lost in both human and fish MPNSTs includes four tumor suppressors, NF1, NF2, SMARCB1 and PTEN, that are strongly associated with the development of human Schwann cell tumors." (PMID 24009526, 2013). "Further, this domain is suggested to be the tumor suppressive region of NF2 in that it is necessary to prevent cellular proliferation in response to mitogenic signaling, as demonstrated by reductions in growth factor receptor signaling, MTT conversion, and colony formation in soft agar." (PMID 23308224, 2013). "NF2, the human ortholog of Mer, is a known tumor suppressor." (PMID 23986776, 2013). "A point mutation in NF2 results in a merlin mutant that has attenuated, but not absent, tumor suppressor activity." (PMID 22745749, 2012). "In familial cases, the NF2 tumours are known to occur at early ages as compared to sporadic cases." (PMID 23304241, 2012). "While previous studies have attempted to link increasing tumor size with hearing loss in patients with NF2, this association has not been established because of the ubiquitous presence of small tumors within all series that are associated with hearing loss." (PMID 23049959, 2012). "Aberrant methylation of the NF2 gene could be considered a relatively early event, whereas hypermethylation of other tumor-related genes might represent secondary changes." (PMID 22567403, 2012). "Tumour cells were analyzed by karyotyping, array CGH and NF2 mutation analysis." (PMID 19772601, 2009). "Mosaicism may be particularly likely in NF2 if the tumours are predominantly on one side of the body." (PMID 19545378, 2009). "If both mutational events are identified in the NF2 gene in a tumour and neither is present in the blood the patient must be mosaic for one of these mutations." (PMID 19545378, 2009).